TTR (transthyretin)
Diseases named in the same sentence as TTR in open-access papers (continued):
Sharing a sentence is not in itself a finding about the gene and the disease.
amyloidosis (continued). "There are only limited therapeutic strategies against TTR amyloidosis such as orthotopic liver transplantation, use of tetramer stabilizers (diflunisal, tafamidis) and TTR silencers (inotersen)." (PMID 30704121, 2019). "Amyloidosis derived from transthyretin (ATTR) is another common type, which results from the misfolded wild-type or mutated transthyretin (TTR) protein." (PMID 30834260, 2019). "Transthyretin is responsible for a series of highly progressive, degenerative, debilitating, and incurable protein misfolding disorders known as transthyretin (TTR) amyloidosis." (PMID 30934952, 2019). "These approvals were based on results from the phase III Neuro-TTR study in patients with hATTR amyloidosis with polyneuropathy during 15 months." (PMID 31399774, 2019). "In hereditary transthyretin amyloidosis, both wild and mutant-type transthyretin accumulate as amyloid in peripheral nerves, heart, kidney, and gastrointestinal tract giving rise to polyneuropathy and cardiomyopathy." (PMID 31608113, 2019). "A recent phase III trial investigating a lipid NPs (LNPs) siRNA formulation to treat transthyretin (TTR)-induced amyloidosis was successful." (PMID 31497026, 2019). "In wild-type TTR (wtTTR) amyloidosis seen in elderly patients, the wild type of TTR is responsible for the beta-sheet structure of the protein deposition." (PMID 31878928, 2019). "Nevertheless, it is conceivable that a synergistic effect can be achieved by the combination of therapeutic molecules that target distinct points of the TTR amyloidosis cascade." (PMID 31117178, 2019). "In conclusion, in this context, curcumin remains a promising scaffold for the development of potent multi-stage disease-modifying drugs for the treatment of TTR amyloidosis." (PMID 30875761, 2019). "Transthyretin (TTR) deposits as amyloid in many elderly people and lead to wild-type TTR-amyloidosis while mutations in the TTR gene can result in hereditary TTR-amyloidosis." (PMID 31600260, 2019). "Many of these diseases such as Parkinson’s disease, Huntington’s, Alzheimer’s, and transthyretin (TTR) amyloidosis are still incurable." (PMID 30934952, 2019). "The therapies for transthyretin-mediated amyloidosis are RNA-based interventions (antisense oligonucleotide or interference RNA) representing a new approach to neurological disorders." (PMID 31334330, 2019). "An example of an FDA approved RNAi based therapy by Alnylam Pharmaceuticals is OnpattroTM for the treatment of polyneuropathy of hereditary transthyretin-mediated amyloidosis in adults." (PMID 31752758, 2019). "In humans, TTR amyloidosis is a group of proteinopathies triggered by partial unfolding, misfolding, aggregation, and accumulation of TTR into a spectrum of cytotoxic aggregates." (PMID 30934952, 2019). "It has been well understood that dissociation of TTR oligomer is the rate-limiting step to TTR amyloidosis because dissociation results in the exposition of important sites for oligomerization." (PMID 30733681, 2019). "Amyloidosis occurs when four monomers dissociated from TTR homotetramers and misfold, aggregate, assemble into amyloid fibrils." (PMID 31718691, 2019). "In the case of transthyretin or fibrinogen amyloidosis, early liver transplantation usually arrests disease progression and can even be curative." (PMID 31200733, 2019). "In patients with HF other mechanisms such as transthyretin amyloidosis or HF with preserved ejection fraction should also be investigated in more detail." (PMID 31861167, 2019). "Deposition of wild-type transthyretin leads to wild-type transthyretin (ATTRwt) amyloidosis or the erstwhile senile systemic amyloidosis." (PMID 31835306, 2019). "The present results provide relevant insight into the neuroprotective potential of C. asiatica, specifically, with regards to TTR amyloidosis." (PMID 30934952, 2019).
amyloidosis (continued). "From recent years, there is a growing body of evidence about the relatively high incidence of wild-type transthyretin (wtTTR) amyloidosis in AS, but there are scarce data on the prevalence of AS in CA, particularly in AL-type amyloidosis." (PMID 31878928, 2019). "TTR amyloidosis often has a higher number of microcalcifications, which would justify its higher uptake of these radiopharmaceuticals." (PMID 31800724, 2019). "Treatment for AL amyloidosis has improved markedly over the last decades, and TTR amyloidosis gene silencers and orally available transthyretin stabilisers are ready to enter the clinical arena after recent positive outcome trials." (PMID 31359320, 2019). "Hereditary transthyretin amyloidosis is a rare, potentially life-threatening autosomal-dominant disease characterised by extracellular deposition of amyloid fibrils composed of transthyretin (TTR)." (PMID 33324896, 2019). "A well-known example is transthyretin (TTR) aggregation that can lead to various amyloid diseases, such as senile systemic amyloidosis." (PMID 31683980, 2019). "RNA interference (RNAi) using siRNA to treat disease have been the most effective method to date with the first ever drug approved by FDA treating hereditary transthyretin-mediated amyloidosis already in the market." (PMID 31850193, 2019). "The therapeutic scenario in hATTR amyloidosis changed recently with the approval of two new TTR gene-silencing drugs, namely inotersen and patisiran." (PMID 31399774, 2019). "Hereditary transthyretin (ATTRm) amyloidosis, also called transthyretin (TTR)-related familial amyloid polyneuropathy (TTR-FAP), is a fatal inherited disease associated with extracellular amyloid deposits derived from TTR1." (PMID 30552363, 2018). "Other clinical remedies to FAC and FAP amyloidosis often employ organs transplantation (e.g., liver), even though not all the affected organs can be transplanted (e.g., choroids plexus, where TTR is produced as well)." (PMID 29967786, 2018). "Pre-excitation and conduction disease put the focus on LAMP2 (Danon disease), PRKAG2, TTR (amyloidosis) or GLA (Fabry disease)." (PMID 30393635, 2018). "Liver transplantation is one of the treatments for ATTRV30M amyloidosis as it removes circulating mutant TTR and interrupts the progression of the disease and improve survival and quality of life." (PMID 30327725, 2018). "A second study of wild-type TTR amyloidosis also demonstrated a monoclonal protein in 25% of patients." (PMID 29795248, 2018). "Any patient with TTR amyloid should have gene sequencing of the TTR gene to distinguish wild-type TTR, as is seen in senile cardiac amyloidosis, from the very rare mutations of TTR that lead to inherited amyloidosis." (PMID 29795248, 2018). "Most of the theoretical body on the mechanism of amyloidogenesis and amyloid toxicity for systemic amyloidoses derives from experimental studies carried out on three types of proteins: LC, TTR and β2-microglobulin (β2-m)." (PMID 30205618, 2018). "Given its efficacy, it is a consideration off label for patients with wild-type TTR amyloid and TTR cardiac amyloid." (PMID 29795248, 2018). "Despite the worldwide distribution of the disease, Portugal remains the main geographic focus of amyloidosis TTR V30M." (PMID 30327725, 2018). "The late onset of TTR amyloidosis, despite the abundance of circulating TTR from birth, is also mysterious." (PMID 30018138, 2018). "Amyloidoses are generated by the misfolding, misassembly and pathological aggregation of several proteins, among which human TTR represents a remarkable example." (PMID 29240759, 2017). "In the present study, we show impairment of CtsE in the PNS, stomach, bone marrow, and bone marrow-derived macrophages of a pre-clinical model of TTR V30M amyloidosis." (PMID 28583160, 2017). "Ambiguous results are most challenging in the elderly as both AL and transthyretin (ATTR) amyloidosis are usually present in this group." (PMID 28647518, 2017).
amyloidosis (continued). "Transthyretin (TTR)-related amyloidosis is the most common form of hereditary autosomic dominant systemic amyloidoses; TTR point mutations lead to the extracellular deposition of amyloidogenic species in different tissues." (PMID 28993312, 2017). "Two types of amyloidosis commonly infiltrate myocardium: immunoglobulin light-chain derived (AL) and transthyretin (ATTR) amyloid." (PMID 28992817, 2017). "For example, there were 4 patients with CMR findings consistent with AS, but who had myocardial biopsy demonstrating TTR amyloidosis." (PMID 29212513, 2017). "Due to the very low disease prevalence and relatively few reports regarding TTR amyloidosis, it is difficult to conduct effective comparisons between epidemiological and molecular data." (PMID 28335735, 2017). "For each ancestral group the synthesis of the TTR expression scores, in terms of median, minimum and maximum, for each tissue involved in TTR amyloidosis is reported." (PMID 28335735, 2017). "Transthyretin (TTR) amyloidosis is a hereditary disease with a complex genotype-phenotype correlation." (PMID 28335735, 2017). "Tafamidis appears as an important option for the treatment of amyloidosis, actingas a kinetic stabilizer of the TTR tetramer." (PMID 28678923, 2017). "Following these observations, the properties of a large number of TTR ligands have been investigated in prospect of their use as drugs effective in the therapy of TTR amyloidosis." (PMID 29240759, 2017). "Macrophages are the main phagocytic cells and expected to infiltrate surrounding pre-fibrillar and TTR amyloid deposits to help on their clearance; however, in most cases, this does not happen." (PMID 28583160, 2017). "For each population the synthesis of the TTR expression scores, in terms of median, minimum and maximum, for each tissue involved in TTR amyloidosis is reported." (PMID 28335735, 2017). "The benefits of lowering mutant TTR levels in patients with hATTR amyloidosis have been demonstrated by OLT, and data from other amyloidoses show that clinical outcomes can be improved by reducing amyloidogenic protein." (PMID 28893208, 2017). "The ventricular myocardium is affected by immunoglobulin light chain (AL) and transthyretin (ATTR) amyloidosis, which has two subtypes, wildtype and mutant." (PMID 28623475, 2017). "Regarding TTR amyloidosis, Japan is one of the endemic foci of the disease with a prevalence of one per million, and different mutations have been identified along with a marked heterogeneity in the disease phenotypic expression." (PMID 28335735, 2017). "In a Phase 2 study (NCT01617967) of 29 patients with hATTR amyloidosis, two doses of patisiran 0.3 mg/kg every 3 weeks reduced mean serum TTR levels by approximately 80%." (PMID 28893208, 2017). "Accordingly, the analysis of the genetically determined TTR expression can help to discern its involvement in human tissues with respect to the genotype-phenotype correlation of TTR amyloidosis." (PMID 28335735, 2017). "The present study cohort of 1617 patients with TTR-related amyloidosis consisted of 1452 patients with MT [728 females, 50.1%; median age 41.5 (range 18.3–86.2) years] and 165 patients with WT [8 females, 4.8%; median age 75.3 (range 48.0–89.6) years]." (PMID 28384285, 2017). "99mTechnetium phosphate derivatives can bind to transthyretin in the myocardium and can be used to identify wild-type and mutant transthyretin-related amyloidosis." (PMID 28928965, 2017). "Native transthyretin (TTR) homotetramer dissociation is the first step of the fibrils formation process in amyloid disease." (PMID 28704493, 2017). "More recently, antibodies against serum amyloid P or in the case of ATTR V30M amyloidosis, a cryptic TTR epitope visible only when TTR is in its monomeric form, are beginning to be explored as possible treatments." (PMID 28539873, 2017).
amyloidosis (continued). "Transthyretin (TTR) and proteins containing a BRICHOS domain are etiologically associated with specific amyloid diseases in the CNS and other organs." (PMID 28360830, 2017). "Our previous investigations focused on the role of non-coding variation in the genotype-phenotype correlation of TTR amyloidosis." (PMID 28335735, 2017). "We conducted a literature survey to define the clinical landscape of TTR amyloidosis across populations worldwide." (PMID 28335735, 2017). "In all, we show a decreased pattern of CtsE expression in bone marrow and bone marrow-derived macrophages of a pre-clinical model of TTR V30M amyloidosis." (PMID 28583160, 2017). "The serial ECGs and/or echocardiography that are often the initial work-ups in these patients play an important role in providing supportive clues since late-onset TTR-related amyloidosis often has cardiac involvement." (PMID 28882124, 2017). "In conclusion, the current study advances the knowledge of TTR amyloidosis in terms of both data regarding the inter-population variability of the disease and methodology that can be applied." (PMID 28335735, 2017). "Transthyretin (TTR) amyloidoses are diseases characterised by the extracellular deposition of fibrillar material containing TTR2." (PMID 28338000, 2017). "Transthyretin (TTR) amyloidosis deoxyribonucleic acid (DNA) sequencing was inconclusive for DNA sequence alteration in the coding region of the TTR gene." (PMID 28877738, 2017). "Many therapeutic strategies are currently investigated in the field of transthyretin amyloidosis including stabilizers of transthyretin tetramers and gene therapies aimed at suppression of transthyretin expression." (PMID 27413736, 2016). "Wild-type and mutant transthyretin (TTR) can misfold and deposit in the heart, peripheral nerves, and other sites causing amyloid disease." (PMID 27122057, 2016). "Transthyretin (TTR) related amyloidosis (ATTR) represents a class of life-threatening and progressing diseases that is associated with the misfolding of TTR, a major blood protein and a carrier of retinol (vitamin A) and thyroxine (T4)." (PMID 27584576, 2016). "The lack of an Food and Drug Administration (FDA)-approved candidate for the treatment of TTR amyloidoses reflects the difficulty of moving from the discovery of in vitro hits to the development of clinically effective and safe drugs." (PMID 26902880, 2016). "While these ATTR forms can be ascribed to a dominant expression of the TTR gene variants, only wild type TTR is expressed in senile systemic amyloidosis (SSA), a type of amyloidosis frequently found in elderly people." (PMID 27584576, 2016). "The anti-aggregational properties of this repositioned drug make it an ideal candidate for the therapeutic treatment of the TTR amyloidoses." (PMID 26902880, 2016). "There are two main conditions related to the misfolding of the TTR protein: wild-type TTR amyloidosis (wt-ATTR) and hereditary forms of TTR amyloidosis." (PMID 27122057, 2016). "We suggest that continued focus on the considerably unfolded TTR monomer, which is highlighted for the first time in this study, is of key importance for further advancement in drug development against TTR amyloidoses." (PMID 26108284, 2015). "These properties make luteolin an interesting candidate for the potential treatment of TTR-induced amyloidosis in humans." (PMID 26020516, 2015). "The effect of homozygosity on phenotype has been reported for patients with hereditary transthyretin or gelsolin amyloidosis, but this is the first report for AFib amyloidosis." (PMID 26199771, 2015). "We propose that strategies other than native tetramer stabilization that directly modulate the interaction of the amyloidogenic protein with the cell surface, can result in alternative or complementary treatment for the TTR amyloidoses." (PMID 25395306, 2015).
amyloidosis (continued). "More recently, their applicability to amyloid disease in the heart has been demonstrated, and they are now undergoing clinical trials for cardiac amyloidosis due to misfolded TTR." (PMID 26664897, 2015). "The prognosis and treatment of the 2 main types of cardiac amyloidosis, immunoglobulin light chain (AL) and transthyretin (ATTR) amyloidosis, are substantially influenced by cardiac involvement." (PMID 26362631, 2015). "Tafamidis ameliorates TTR amyloidosis by acting as an orthosteric stabiliser of TTR dimers through binding to the thyroxine-binding site located at the TTR dimer–dimer interface." (PMID 25935873, 2015). "Reduction in the abundance of amyloid fibril precursor proteins arrests amyloid deposition and halts disease progression in all forms of amyloidosis including TTR type." (PMID 26400472, 2015). "Transthyretin V30M (ATTR V30M) amyloidosis is a phenotypically diverse disease with symptoms ranging from predominant neuropathy to exclusive cardiac manifestations." (PMID 26600306, 2015). "According to our results, target proteins recognized as causative agents of amyloidosis, such as immunoglobulin light chains, SAA and TTR, were successfully identified, and their molecular weights were higher than 10 kDa." (PMID 25984759, 2015). "Here, we investigated the effect of two small stabilizing ligands, tafamidis and diflunisal, which are currently being trialled for the treatment of TTR amyloidosis." (PMID 26286619, 2015). "TTR (transthyretin) amyloidoses are diseases characterized by the aggregation and extracellular deposition of the normally soluble plasma protein TTR." (PMID 25395306, 2015). "Our data have implications for the design of new therapeutic strategies to prevent the earliest events producing tissue damage in the TTR amyloidoses." (PMID 25395306, 2015). "In the case of TTR amyloidosis with prominent heart involvement, it has been shown that wild type TTR itself accumulates on existing amyloid plaques after transplantation." (PMID 26437390, 2015). "There is a body of literature linking protein misfolding and amyloidosis, including TTR amyloidosis, to the generation of ROS and apoptotic cell death." (PMID 25395306, 2015). "A similar approach was used to design therapies for transthyretin-related amyloidosis by stabilizing the tetrameric state of the protein." (PMID 26576950, 2015). "The phenotype of TTR-related amyloidosis is diverse and the extracellular deposition in various tissues, mainly peripheral neurons, gastrointestinal tract and the heart, shows plaques comprising TTR." (PMID 26437390, 2015). "The phenotype, inheritance and organ specificity of TTR amyloidosis is highly different and three major clinical forms, TTR-FAP, TTR-FAC and TTR-SSA, have been described." (PMID 26437390, 2015). "Over the last few years, many small compounds have been proposed as disease-modifying therapeutic agents specific for TTR-related amyloidosis." (PMID 24459092, 2014). "Transthyretin amyloid (ATTR) amyloidosis is a systemic disorder with two main forms; hereditary and wild-type (wt) ATTR amyloidosis." (PMID 24767411, 2014). "Effective medical treatment of patients with TTR amyloidosis requires an accurate diagnosis based on various studies and techniques, such as histopathology, genetic testing, and mass spectrometry." (PMID 25228988, 2014). "Transthyretin (TTR) amyloidoses comprise a wide spectrum of acquired and hereditary diseases triggered by extracellular deposition of toxic TTR aggregates in various organs." (PMID 24459092, 2014). "Here, we extended the examination of CLR01 as a potential disease-modifying agent for TTR-related amyloidosis, first by comparing its effect side-by-side with EGCG in vitro." (PMID 24459092, 2014). "The sections that follow provide details of conventional and potential treatments of TTR amyloidosis." (PMID 25228988, 2014).